MC4R (melanocortin 4 receptor)
Diseases named in the same sentence as MC4R in open-access papers (continued):
Sharing a sentence is not in itself a finding about the gene and the disease.
Obesity (continued). "While the Mc4r knockout mice exhibit marked obesity, resulting from hyperphagia and hypometabolism, genetic disruption of the Mc3r lead to a modest obesity phenotype, suggesting that MC4R constitutes the major MCR receptor involved in energy homeostasis." (PMID 28690493, 2017). "The first mutation analysis in 306 obese individuals further confirmed the role of MC4R in obesity." (PMID 28615046, 2017). "Authors analyzed the genetic variants that cause lifelong high BMI in FTO (fat mass and obesity-associated gene, rs9939609), MC4R (Melanocortin-4 Receptor gene, rs17782313) and TMEM18 (transmembrane protein 18, rs6548238) genes to evaluate the consequences of the obesity in COPD patients." (PMID 28335527, 2017). "The aim of this study, therefore, was to investigate ab initio whether the Mc4r gene plays a role in the maternal programming of offspring obesity and consequent NAFLD." (PMID 28930194, 2017). "On the other hand, the SNP of MC4R A822G did not exhibit any significant association with obesity among studied subjects and showed only the presence of homozygous AA genotype." (PMID 29937877, 2017). "Haploinsufficiency of the Mc4r is the most common monogenetic obesity syndrome in man and is responsible for 0.5–2.5% of all early onset morbid obesity making it an important consideration in personalized obesity care." (PMID 28829041, 2017). "Notably, the obesity induced by the disruption of leptin signaling resembles that observed following Pomc or Mc4r nullification." (PMID 28690493, 2017). "We conclude that an association of the MC4R gene polymorphism with dog obesity or body weight is unlikely, in spite of the fact that some associations were found in small cohorts of Beagles and Golden Retrievers." (PMID 28755272, 2017). "Furthermore, mutations leading to complete loss of function are correlated with a more severe phenotype, and targeted disruption of the melanocortin-4 receptor also results in obesity in mice." (PMID 27926527, 2017). "Like FTO, MC4R has been extensively studied in obesity research." (PMID 28615046, 2017). "Also, the detection of genetically produced dysfunction by proteins such as MC4R which is involved in energy regulation, as a marker in diagnostic strategies, and as a predictor of remedies will be important for future management of obesity and might be a target for future gene therapy." (PMID 28924523, 2017). "A GWAS which identified 14 known obesity susceptibility variants and 18 new loci that were associated with BMI found that some of these loci are mapped at the LEP–POMC pathway, i.e., LEP and its receptor LEPR, POMC and MC4R." (PMID 28615046, 2017). "Single gene alterations with Mendelian inheritance account for less than 5% of non-syndromic cases of severe EOO, including mutations in the LEP (MIM 164160) or LEPR (MIM 601007) genes, as well as in MC4R (MIM 155541) which are the most common cause of monogenic obesity." (PMID 28489853, 2017). "Moreover, the MC system, especially the melanocortin 4 receptor (MC4-R), are currently a promising target system for the development of drugs intended to treat obesity and eating disorders in humans." (PMID 28936166, 2017). "The significance of FTO rs17817449, GNB3 rs5443 and MC4R gene mutation in Saudi obese populations has not been examined despite its association with obesity in other parts of the world." (PMID 29937877, 2017). "The intake of carbohydrates and proteins did not exhibit any significant association with MC4R genotypes and the risk of obesity (data not shown)." (PMID 27213003, 2016). "An enduring AgRP-induced blockade of MC4R leads to hyperphagia and obesity." (PMID 27147943, 2016). "The fat mass and obesity associated (FTO) gene variant rs9939609 has also been associated with increased risk of NAFLD and the Melanocortin 4 Receptor (MC4R) rs12970134 variant with increased ALT levels, independently of BMI, in children aged 7–18 years old with NAFLD." (PMID 27314342, 2016).
Obesity (continued). "This patient's deletion encompassed MC4R and he presented with obesity." (PMID 27738543, 2016). "Melanocortin 4 receptor (MC4R) variants contribute to human obesity, and rats lacking functional MC4R (Mc4rK314X/K314X) are obese." (PMID 27886210, 2016). "The mutation in the Mc4r gene produces a premature stop codon, and the mutant SIM1 protein lacks transcriptional activity, showing that the haploinsufficiency of SIM1 and MC4R results in obesity." (PMID 27585985, 2016). "Obesity in mouse models can be generated by deletions or mutations of either the POMC gene or MC3R/MC4R genes, and a similar phenotype is seen in humans that have deficiency of the MC4R." (PMID 26819774, 2016). "For example, mutations in SIM1, leptin receptor (LEPR), pro-opiomelanocortin (POMC), melanocortin 4 receptor (MC4R), and more recently, POU3F2 have all been associated with severe obesity, suggesting a convergence on the leptin-melanocortin pathway in association with oxytocin." (PMID 27857842, 2016). "Although MRAP2 has been shown to interact with MC4R, a G protein-coupled receptor with an established role in energy homeostasis, appetite regulation and lipid metabolism, the mechanisms through which loss of MRAP2 causes obesity remains uncertain." (PMID 27106110, 2016). "The overlap between monogenic obesity genes and obesity genes identified via GWAS (e.g. MC4R and BDNF) might imply a role of hypothalamic dysfunction affecting the regulation of energy balance in polygenic obesity, which can drive T2D." (PMID 26363598, 2015). "Genes functioning in the leptin-melanocortin pathway such as those encoding leptin (LEP), leptin receptor (LEPR), melanocortin 4 receptor (MC4R), pro-opiomelanocortin (POMC) and brain-derived neurotrophic factor (BDNF) have been implicated in the monogenic form of obesity." (PMID 26363598, 2015). "When developing an anti-obesity therapeutic drug with selective MC4R/MC5R properties, effects on lipolysis in white adipose tissue may be physiologically relevant." (PMID 26459134, 2015). "The top-20 scoring GDAs from DisGeNET are very well-studied gene-disease relationships, like Alzheimer Disease and APP [amyloid beta (A4) precursor protein], obesity and MC4R (melanocortin 4 receptor), and Type 2 Diabetes Mellitus and IRS1 (insulin receptor substrate 1)." (PMID 25877637, 2015). "In Mc4r−/− mice, obesity is attributable to hyperphagia and reduced energy expenditure." (PMID 26113808, 2015). "A current hypothesis is that the obesity phenotype is due to abnormal function of the melanocortin-4 receptor (MC4R) in the hypothalamus." (PMID 25337124, 2014). "It has been argued that synthetic associations with MC4R nsSNPs are not likely to underlie the associations between SNPs 3′ of MC4R and obesity." (PMID 24820477, 2014). "Common and rare variation in MC4R contributes to obesity in American Indians." (PMID 25103139, 2014). "At the cellular level no consistent change in MC4R signaling can account for the association of rare variants with obesity." (PMID 24705671, 2014). "Five common variants: rs17782313 and rs1770633 (melanocortin 4 receptor (MC4R); rs7566605 (insulin induced gene 2 (INSIG2); rs9939609 and rs1121980 (fat mass and obesity associated (FTO) were genotyped in 2 cohorts of Swedish women: PEAK-25 (age 25, n = 1061) and OPRA (age 75, n = 1044)." (PMID 24516669, 2014). "We conclude that carrying a rare variant of MC4R, while associated with obesity, does not affect weight-loss after gastric bypass surgery." (PMID 24705671, 2014). "The contribution of the central melanocortin system in etiology and pathogenesis of T2DM and obesity is fully confirmed by the data on the immunization of rats with peptides corresponding to the N-terminal extracellular domain MC4R and to the first and third extracellular loops of MC3R." (PMID 24191197, 2013).
Obesity (continued). "Furthermore, we found nominal associations between obesity risk or BMI variation and the following SNPs: ENPP1 rs7754561, MC4R rs17782313 and NEGR1 rs2815752." (PMID 23375129, 2013). "We examined how obesity affects the vasorelaxation phenotype in MC4R+/− obese pregnant rats." (PMID 24159378, 2013). "Among them, FTO, MC4R, MTCH2 and HTR2C are the main associated loci with BMI and obesity." (PMID 24267414, 2013). "Furthermore, GWAS studies in obesity based on more than 200,000 individuals have confirmed that genes in this pathway such as POMC and MC4R are associated with obesity." (PMID 23796690, 2013). "Indeed, elevated insulin level and impaired insulin sensitivity were detected in the young lean MC4R knockout mice, even before the development of pronounced hyperphagia and obesity." (PMID 24191197, 2013). "Furthermore, we found nominal associations between risk of obesity or BMI and the following SNPs: ENPP1 rs7754561, MC4R rs17782313 and NEGR1 rs2815752." (PMID 23375129, 2013). "Accordingly, the goal of this study was to test the hypothesis that MC4R KO impacted cardiovascular control in obesity." (PMID 24400148, 2013). "When considering MC4R involvement in generating an obesity phenotype, it is useful to note that polar bears have a need for increased body fat content for thermal insulation, water buoyancy, and energy storage requirements as compared to humans and to other organisms that share a conserved V95." (PMID 23633938, 2013). "Genomewide association studies in adults have shown associations between BMI or weight and common genetic variants involved in eating behaviors, including satiety regulation and dietary intake [eg, fat mass and obesity associated (FTO) and melanocortin 4 receptor (MC4R)]." (PMID 24047917, 2013). "On the other hand, analyses of the entire coding sequence of the MC4R gene revealed numerous polymorphisms, but their association with obesity was not evident." (PMID 24142065, 2013). "None of the 5 MC4R obesity risk variants associated with increasing BMI in AGA were significant in those born SGA." (PMID 23339409, 2013). "Amongst the adiposity-related genetic variants, we chose single nucleotide polymorphisms (SNPs) within the most common major adiposity genes FTO, MC4R and TMEM18, all of which have been recognized to be associated with obesity and explaining a variance of about 1–2%." (PMID 22723994, 2012). "When adherence to the MedDiet was low (=<9 points), carriers of the variant allele (obesity-risk allele) had a higher risk of prevalent type 2 diabetes (OR=1.21, 95%CI: 1.03-1.40; P=0.019 for FTO and OR=1.17, 95%CI:1.01-1-36; P=0.035 for MC4R) than homozygous subjects for the major allele." (PMID 23130628, 2012). "In conclusion, we have confirmed the association of the FTO rs9939609 polymorphism with higher BMI, waist circumference and obesity even in a high cardiovascular risk population and described an additive effect of the FTO rs9939609 and the MC4R rs17782313 on these obesity-related measures." (PMID 23284998, 2012). "The current study focused on variants located within and around FTO, MC4R and TMEM18 that are amongst the genes most strongly associated with obesity traits and also identified in earlier meta-analyses, despite the fact that the variance explained by these loci is small (1–2%)." (PMID 22723994, 2012). "For example, the FTO gene encodes for an enzyme that is able to remove methyl groups from DNA, long-term exposure to high-fat diet can decrease the melanocortin-4 receptor (MC4R) gene methylation and high-fat diet–induced obesity can modify leptin methylation patterns." (PMID 24392269, 2012). "We expected that the effects of FTO and MC4R on body fat mass would be more apparent if the population were stratified by SCM type, as a previous report has demonstrated distinct susceptibilities to obesity among subjects with different SCM types." (PMID 19822564, 2011).
Obesity (continued). "As might be expected, genetic variation resulting in loss of function for the MC4R, LEP, and POMC genes contributes to weight gain and obesity." (PMID 22043166, 2011). "Recently, several independent large-scale genome-wide association studies (GWAS) reported an association of fat mass and obesity associated (FTO; MIM: 610966) and melanocortin-4 receptor (MC4R; MIM: 155541) gene polymorphisms with obesity and BMI in Caucasian populations." (PMID 21347432, 2011). "In the present study, we examined single nucleotide polymorphisms (SNPs) in the adiponectin, LEPR, MC4R and FTO genes in association with obesity in a cohort of young South African Asian Indian patients with acute myocardial infarction (AMI), with and without the metabolic syndrome." (PMID 21298202, 2011). "MC4R is therefore a highly relevant candidate gene for common obesity." (PMID 22043164, 2011). "The evolutionary history of the MC4R obesity locus has been well documented in the literature." (PMID 22043165, 2011). "Early diagnosis is fundamental for personalized prevention and effective therapeutic management, and in young non-obese individuals carrying MC4R monogenic mutations, an appropriate medical follow-up to prevent or at least delay the onset of obesity." (PMID 22043165, 2011). "Nine loci have been associated with extreme obesity at the genome-wide level, five of them influencing BMI / waist circumference as well as risk for extreme obesity (FTO, MC4R, TMEM18, MSRA, NPC1), four loci being more specific of genetic risk for extreme obesity (MAF, PTER, PRL, SDCCAG8)." (PMID 22043164, 2011). "Targeted disruption of Mc4r results in obesity in mice, loss-of-function coding mutations in MC4R lead to the more common form of monogenic human obesity and significant evidence of linkage for obesity-related traits has been reported on chromosome 18, where the MC4R gene resides." (PMID 22043164, 2011). "Whether the constructed obesity haplotype points to an ancestral obesity haplotype or if it reflects the impact of two relatively independent loci in the vicinity of the MC4R is beyond the scope of our analyses." (PMID 21085626, 2010). "MC4R agonists specifically designed are being investigated for potential treatment of obesity." (PMID 27713245, 2010). "As both FTO and MC4R are known to affect type 2 diabetes risk through modulation of obesity, association was also calculated without adjustment for BMI." (PMID 20161779, 2010). "In addition, we assessed the effect of the markers in 31,182 obese, lean, normal weight, and unselected individuals from population-based samples and showed that the variants near FTO, MC4R, TMEM18, and SDCCAG8 were consistently associated with obesity." (PMID 20421936, 2010). "Besides GHRL, the set of causal genes shared by obesity and cachexia comprised ADRB2, MC4R, and CNTF." (PMID 20815942, 2010). "Mutations on MC4R gene represent the most frequent cause of monogenic non-syndromic obesity, with prevalence, among obese children, reaching in some cases the 5%." (PMID 19284607, 2009). "This limitation does not allow us to firmly conclude that there are no phenotypic characteristics of MC4R mutations other than obesity per se." (PMID 19284607, 2009). "Several genes isolated through these studies, including FTO and MC4R, may eventually help scientists to explain the global scale of the obesity epidemic and the biological mechanism for the heritability of obesity in families." (PMID 19527601, 2009). "Also, although recent genome wide association studies have identified common genetic variation in the melanocortin 4 receptor (MC4R) and FTO (the fat mass and obesity associated) genes, an association with the dopamine transporter was not reported." (PMID 19183461, 2009). "Overall, the role of MC3R in feeding behaviour and obesity is less clear than for MC4R." (PMID 17764572, 2007). "Genetic deletion of MC4R in mice and humans results in severe hyperhagic obesity." (PMID 17448988, 2007).
Obesity (continued). "It is also possible that genetic defects in the intracellular trafficking mechanisms, required to present MC4R on the cell surface, could also lead to human obesity." (PMID 17764572, 2007). "In contrast with rare monogenic obesities, even careful clinical analysis does not easily detect obesity stemming from MC4R mutations because of the lack of additional obvious phenotypes." (PMID 17196040, 2006). "These genes could be the same genes as those involved in obesity, exemplified by a study of the relation between variation in the MC4R gene, the most common form of monogenic obesity, and the outcome of surgical treatment." (PMID 16871334, 2006). "Current MC4R therapeutic peptides are of interest, but have been found to be anorexigenic and to stimulate erectile activity; therefore, the development of therapies targeting monogenic obesity will need to circumvent such undesirable side effects." (PMID 17196040, 2006). "Currently, there is no causal therapy for children with severe obesity due to MC4R deficiency." (PMID 41489710, 2026). "For example, patients with MC4R variants may have developmental or linear growth differences compared with patients with obesity who do not have MC4R deficiency." (PMID 40528426, 2025). "Therefore, the activation of SIM1 or MC4R expression may represent a potential cure for inherited forms of obesity." (PMID 40650152, 2025). "The MC4R gene has been associated with susceptibility to nonsyndromic obesity." (PMID 40585884, 2025). "Furthermore, data from the UK Biobank suggest a role for MC4R in connecting obesity and depression, while a study among Iranian overweight and obese women showed an association between depression and the MC4R risk allele, particularly in individuals with unhealthy diets." (PMID 40956393, 2025). "Interestingly, adult MC4R carriers are not at an increased risk of obesity-related complications such as diabetes but linked to cardiovascular dysfunctions." (PMID 40001512, 2025). "Because of the rarity of MC4R pathway diseases, hyperphagia may be misdiagnosed as a more common or well‐known overeating behavior or disorder or overlooked owing to other health problems such as obesity‐related comorbidities." (PMID 40528426, 2025). "We found that adolescents with MC4R deficiency had lower diastolic blood pressures compared to control individuals in the GOOS cohort without mutations in known obesity genes matched for age and BMI, in keeping with previous studies in adults by ourselves and others." (PMID 41102563, 2025). "Considering the findings that the C allele was identified as a risk allele for obesity and that the CC genotype was associated with higher fBMI, bioinformatic predictions indicate that these effects are not due to a structural change in the MC4R protein." (PMID 40035963, 2025). "In a cohort of children with severe monogenic obesity, mortality rates were 26% and 9% for leptin or leptin receptor deficiency, respectively, while no deaths were reported in comparably obese children with melanocortin 4 receptor (MC4R) deficiency." (PMID 40944251, 2025). "Mouse models of BBS have demonstrated leptin resistance in the hypothalamic MC4R pathway, which drives hyperphagia and obesity and may be explained by impaired leptin signaling in the hypothalamic neurons resulting from disrupted functioning of the neuronal cilia." (PMID 40186386, 2025). "Genetic alterations, such as MC4R dysfunction, disrupt appetite regulation, potentially explaining the observation of differences in the long-term outcome in percentage of weight loss in comparison to patients with a non-genetic obesity." (PMID 40822950, 2025). "Moreover, we showed that obesity-associated MRAP2 mutations impair this effect, and consequently have increased MC4R internalization, which could explain the reductions in MC4R signaling by these MRAP2 mutant proteins." (PMID 39807633, 2025).